ENSG00000275134
Gene: Miscellaneous RNA gene on chromosome 14 (100,898,958 to 100,899,079, forward strand). Ensembl gene ENSG00000275134.
Gene Ontology:
Cellular component: nucleus